NF2 (NF2, moesin-ezrin-radixin like (MERLIN) tumor suppressor)
Diseases named in the same sentence as NF2 in open-access papers (continued):
Sharing a sentence is not in itself a finding about the gene and the disease.
meningioma (continued). "This study aimed to probe the importance of NF2 alteration in prognosis of WHO grade I meningiomas." (PMID 35570314, 2022). "This retrospective study demonstrated that multiparametric MRI-based radiomics analysis could be a promising approach for preoperative prediction of NF2 inactivation in patients with meningioma." (PMID 36267986, 2022). "NF2 alterations are the main finding also in grade 3 meningiomas." (PMID 35565385, 2022). "Previously, NF2 alteration, multiple copy number variations (CNV; e.g. 22q loss, 1p loss, etc.), high FOXM1 expression, low immune cell infiltration, and loss of H3K27me3 were reported as characteristics of aggressive behaviour of meningiomas." (PMID 35570314, 2022). "The Nf2 homozygous germline null mouse model is lethal, and the hemizygous Nf2 knock-out mouse (Nf2+/−) does not develop meningiomas, because the loss of the wild-type allele does not occur spontaneously in the murine meningeal cells, unlike in humans." (PMID 34359639, 2021). "In addition, quantification of mRNA expression confirmed decreased SMARCE1 expression in tumors within the clear cell cohort as compared to NF2-altered meningiomas (adjusted p = 1.34e-11)." (PMID 33319313, 2021). "Further research will be needed to describe why many NF-2 mutated meningiomas with chromosome 22 deletion do not experience a transformation to high-grade histopathology." (PMID 34638590, 2021). "KLF4 K409Q missense mutations are present in up to 50% of NF2 nonmutated meningiomas, often co-present with TRAF7 mutations, and lead to upregulation of HIF-1a pathway." (PMID 34679551, 2021). "It is not yet well understood how the inactivation of NF2 can guide the development of meningiomas." (PMID 34679551, 2021). "The clinical diagnostic criteria include bilateral vestibular schwannomas (prior to age 70); or a known first-degree family member with NF2 and either a unilateral vestibular schwannoma or two or more meningiomas, cataracts, schwannomas, or cerebral calcifications." (PMID 34885143, 2021). "Taken together, our data show that pediatric meningiomas can be separated into groups with distinct morphological and molecular features, and that pediatric meningiomas are distinct from adult counterparts despite sharing a high frequency of NF2 alterations." (PMID 34495383, 2021). "Recently, a number of Non-NF2 alterations have been identified in sporadic adult meningiomas." (PMID 34495383, 2021). "Meningiomas (MNs), arising from the arachnoid/meningeal layer, are nonresponsive to chemotherapies, with ∼50% showing loss of the Neurofibromatosis 2 (NF2) tumor suppressor gene." (PMID 33273014, 2021). "Meningiomas from NF2 patients clustered exclusively within groups 1 and 2A." (PMID 34495383, 2021). "NF2 patients tend to develop meningiomas at an earlier age than those with sporadic meningiomas." (PMID 34072574, 2021). "The genetic landscape of meningioma is characterized by the presence (in about 60% of cases) or absence of NF2 mutation." (PMID 34679551, 2021). "One clinical challenge created by the genetic landscape of high-grade tumors is that the majority of targeted therapies for meningiomas focus on interrupting oncogenic pathways associated with non-NF-2 mutations (as will be discussed later)." (PMID 34638590, 2021). "In the 1990s, the NF2 gene was discovered to be a major driver of meningioma development." (PMID 33801089, 2021). "Additionally, histone deacetylases (HDACs) have been implicated in meningiomas through the regulation of transcriptional changes, downstream of PI3K/Akt, in the setting of NF2 deletion." (PMID 34300316, 2021). "Mutations of KDM5C (Lysine Demethylase 5C), KDM6A or Somatic SWI/SNF-related matrix associated actin-dependent regulation of chromatin subfamily B member 1 protein (SMARCB1) can lead to epigenetic modifications that are present in about 10% of non-NF2 meningiomas." (PMID 34679551, 2021). "Patients with NF2 will often suffer from both meningiomas and schwannomas." (PMID 34264955, 2021).
meningioma (continued). "Meningiomas are a common primary brain tumor; many NF2 patients suffer from multiple meningiomas." (PMID 33445724, 2021). "Collectively, our results suggest that the anti-tumor activity of brigatinib in NF2 associated schwannoma and meningioma is mediated through blockade of multiple RTKs and non-RTKs." (PMID 34264955, 2021). "Unlike sporadic mutations, NF2 mutations are far more likely to produce multiple meningiomas and occur in a younger population; the mean age of meningioma diagnosis is 30 years." (PMID 33445724, 2021). "The results of this single-agent screen demonstrated that the pharmacological responses clustered cells by tumor type (meningioma versus schwannoma) rather than NF2-expressing versus NF2-deficient cells." (PMID 34264955, 2021). "Fifty percent of the cases were located in the convexities and had concurrent NF2 mutations, while both skull base meningiomas did not have NF2 mutations." (PMID 33809258, 2021). "For NF2, the high priority of vestibular schwannoma and other tumour manifestations agrees with the main focus of current NF2 trials on vestibular schwannoma and meningioma." (PMID 33903738, 2021). "Unlike sporadic meningiomas, they found a lack of mutations, the most obvious and apparent link is the inactivated NF2 gene." (PMID 33445724, 2021). "Beyond the NF2, the SMARCE1 (SWI/SNF-related, matrix-associated, actin-dependent regulator of chromatin, subfamily E, member 1) gene mutation was found in young adults (16–24 years) with meningioma." (PMID 34574050, 2021). "Two brain invasive meningiomas, both localized at the anterior medial skull base (olfactory groove), had alterations in the PI3K-AKT-mTOR pathway, consisting of AKT1 E17K mutations (1M; 7M), which were mutually exclusive to NF2 alterations." (PMID 33670055, 2021). "In combination with the predominance of M1 pro-inflammatory macrophage infiltrate in meningiomas with 22q deletions, CI could be more efficacious in meningiomas with NF2 inactivation or deletions." (PMID 32982948, 2020). "Interestingly, NF2 mutant meningiomas appear to have more histopathological findings of fibrous or transitional rather than some meningothelial histologic variants, likely due to lack of cytoskeleton linker resulting in a more mesenchymal phenotype." (PMID 33194703, 2020). "Importantly, we detected KDM6A alterations in 23/472 of all NF2-mutant (4.9%) versus 7/377 in NF2-wt meningiomas (1.9%) (p = 0.0234)." (PMID 33087175, 2020). "Further immunohistochemistry analysis comparing AKT1 E17K mutants to WHO grade I NF2-negative samples showed significantly lower levels of CD163-positive activated M2 macrophages in meningiomas with mutated AKT1 E17K, signifying a more immunosuppressive tumour microenvironment in NF2 meningiomas." (PMID 32070062, 2020). "We termed these poor prognosis meningiomas as “NF2-agnostic,” reflecting lack of associations with the presence or absence of NF2 alterations in this cohort." (PMID 33087175, 2020). "These non-NF2 meningiomas represent approximately 40% of mainly grade I sporadic meningiomas, with the other 15–20% of meningiomas containing presently unknown genetic drivers of tumorigenesis." (PMID 32070062, 2020). "Despite the identification of NF2 mutations or loss of function, recent sequencing studies also revealed mutations involving TRAF7, KLF4, AKT1, SMO, POLR2A, and the ARID1A and TERT promoters of in meningiomas." (PMID 32923390, 2020). "Moreover, male patients (n = 245/384, 64%) were significantly more affected by NF2-mutant meningiomas than female patients (n = 227/466, 48.7%, p = 0.0001)." (PMID 33087175, 2020).
meningioma (continued). "Furthermore, were observed a significant association of alterations in the chromatin regulator ARID1A in NF2-mutant meningiomas (n = 34/472, 7%) versus NF2-wt meningiomas (n = 12/377, 3.2%, p = 0.0138)." (PMID 33087175, 2020). "Interestingly, genetic abnormalities in meningiomas are different in relation to the location and the type of the lesion: in fact, SMO and AKT1-MTOR mutations are quite common in non-NF2, genomically stable meningiomas of the skull base." (PMID 32244473, 2020). "NF2 mutant atypical meningiomas displayed a hypermethylated phenotype." (PMID 32493231, 2020). "The majority of patients with meningiomas present with a solitary tumor, multiple meningiomas may be seen, particularly in NF2, however, multiple extra axial lesions could also be a result of metastatic disease." (PMID 33194703, 2020). "The lack of NF2 mutation is frequent in skull base meningiomas with meningothelial and secretory features." (PMID 32642718, 2020). "NF2-associated tumors frequently exhibit a higher mitotic index than histologically comparable sporadic tumors, and atypical meningiomas are not uncommonly encountered in this setting." (PMID 31161239, 2020). "We did observe meningioma-related mutations in oncogenic AKT1, SMO, TRAF7, and NF2 gene." (PMID 32742192, 2020). "Moreover, mutations of NF2 are most frequent in fibroblastic/transitional meningiomas, KLF4 and TRAF7 in secretory meningiomas, and AKT1 mutations in grade I meningothelial meningiomas of the skull base and spine." (PMID 32244473, 2020). "Among these, the most frequent changes observed are losses in 1p and 14q, apart from alterations in chromosome 22q which correspond to the most frequently observed ones in meningiomas, usually affecting the NF2 gene, and are present in half of grade II and almost all grade III meningiomas." (PMID 32670372, 2020). "It is possible that these older patients have simply had more time and opportunity to develop multiple sporadic schwannomas or meningiomas, even without predisposing NF2 mutation." (PMID 33013614, 2020). "Indeed, previous work has observed that increased H3K27me3 levels and a hyper-methylated phenotype occupying the polycomb repressive complex (PRC2), is one of the hallmarks of NF2-mutant high-grade meningiomas." (PMID 33087175, 2020). "Notably from a clinical standpoint, alterations of genes encoding regulators of the cyclin-dependent kinase (CDK) inhibitor pathway occurred in ~ 20% of NF2-mutant high-grade/progressive meningiomas." (PMID 33087175, 2020). "In addition, the majority of these NF2-wt tumors were classified as WHO grade 1 meningioma (n = 31, 70.4%) and were located almost exclusively in the skull base." (PMID 33087175, 2020). "Based on these results, we look further to find more therapeutic avenues in NF2-mutant meningiomas." (PMID 32642722, 2020). "The genetic basis for these differences is not entirely clear, as sporadic grade I meningiomas also frequently exhibit monosomy 22 and loss of function of NF2." (PMID 31161239, 2020). "Moreover, NF2 mutations were recently shown to contribute to a decreased PFS in a sample of WHO grade I and II meningiomas." (PMID 31191822, 2019). "Finally, by establishing and characterizing the NF2-mutated anaplastic meningioma cell line NCH93, we provide a novel powerful cell model for meningioma research." (PMID 30991738, 2019). "Therefore, initial efforts to create a Nf2 deletion-based GEMM of meningiomas relied upon a conditional knockout approach." (PMID 31652973, 2019). "This information is useful for appropriate resection and accurate evaluation of meningioma prognosis, highlighting that non-NF2 tumors may benefit from targeted treatments due to their lower mutation rates but higher likelihood of recurrence." (PMID 31565188, 2019).
meningioma (continued). "The microtubule-disrupting non-steroidal 2ME2 analogs could provide another option for treating NF2-related tumours, both vestibular Schwannomas and meningiomas, either alone, or in conjunction with other agents." (PMID 31730023, 2019). "The first indication that meningiomas may have a genetic contribution came from neurofibromatosis type 2 (NF2)." (PMID 31652973, 2019). "There is an association between patients that have neurofibromatosis type 2 and the development of meningioma due to variable mutations in the NF2 gene and the subsequent production of a non-functional protein known as merlin." (PMID 31788444, 2019). "In addition to the common genetic alteratons in NF2 in sporadic meningiomas, a number of other clinically actionable genetic events have been described in meningiomas over the past 10 years." (PMID 31139260, 2019). "Furthermore, several distinct histological subtypes were seen in patients who underwent resection of multiple meningiomas, suggesting that NF2 inactivation is an early tumorigenic event that occurs prior to commitment to a specific histopathologic subtype." (PMID 31652973, 2019). "Unfortunately, within NF2 mutated meningiomas none of these identified mutations can predict the chance of recurrence, which can vary widely." (PMID 31970090, 2019). "However, genomic alterations in atypical and anaplastic meningiomas are multifactorial, involving numerous genetic changes, and the role of NF2 in tumor progression requires further investigation." (PMID 31191822, 2019). "Most high-grade meningiomas were characterized by NF2 loss, without any other significantly recurring somatic mutations, in contrast to benign meningiomas." (PMID 31652973, 2019). "Whether malignant transformation may also be more common after irradiation of NF2 related meningiomas than sporadic tumors is however unknown." (PMID 30356733, 2018). "We identified deletion of the NF-2 gene in two MPMNs and one CNS meningioma." (PMID 30542514, 2018). "Sporadic multiple meningiomas have been associated with somatic NF2 mutations and, to date, there has been no case related to somatic SMARCB1 mutations." (PMID 30416484, 2018). "Interestingly, NF2 has been reported as a direct target of PKA23 evidencing the importance of PKA signaling in meningioma aggressiveness." (PMID 29391485, 2018). "This suggested that, both NF2 and PR, may involve in the same pathway and have synergistic effects in the pathogenesis of meningioma." (PMID 30687635, 2018). "Thus, according to this study, five different molecular subgroups of meningiomas: NF2/SMARCAB1, KLF4/TRAF7, PI3K/TRAF7, Hedgehog, and POLR2A." (PMID 30279357, 2018). "Further study is needed to investigate whether PR and NF2 expression in meningioma has a progesterone dose-dependent mechanism, therefore, animal model is modest and simple way to observe this association." (PMID 30687635, 2018). "In meningioma, TRAF7 mutations can co-occur K409Q mutation in KLF4, a transcription factor known for its role in inducing pluripotency, and are mutually exclusive with NF2 mutations, chromosome 22 loss, and SMO mutations and was less common in HGMs." (PMID 30082628, 2018). "No detailed analysis has been performed to date, possibly due to the fact that mutations in the Nf2 gene have thus far been related to the development of schwannomas, meningiomas and gliomas—but have not been described in patients harboring oligodendrogliomas." (PMID 29715273, 2018). "Increased level of IL-1β may subsequently trigger NF2 inactivation followed by low merlin's activity, which results in acceleration in cell growth and the development of meningioma." (PMID 30687635, 2018). "Recently, somatic protein-altering mutations were found in a subset of meningiomas without NF2 mutations." (PMID 28340489, 2017). "Multiple meningiomas are very rare and usually occur in the context of NF2." (PMID 27921248, 2017).
meningioma (continued). "Indeed, genomically unstable, hypermethylated NF2 mutant meningiomas, which display activation of the cell cycle as well as the PRC2 pathways, account for the majority of the genomic landscape of primary atypical meningiomas." (PMID 28195122, 2017). "Among tumors with chromosome 22 loss, we detected non-NF2 driver mutations at a higher rate in meningiomas without NF2 mutations than in meningiomas with NF2 mutations, suggesting that NF2 was not equivalently inactivated in the two groups." (PMID 28713588, 2017). "Importantly, decreased H3K27ac binding was associated with decreased GFRA1 expression in atypical NF2 versus benign NF2 meningiomas (FDR 6.2 × 10−5 fold change log FC=9.54)." (PMID 28195122, 2017). "Two case series evaluated meningiomas from NF2 patients only for the allelic imbalances most commonly observed in sporadic meningiomas, and confirmed frequent somatic inactivation of the NF2 gene, as well as losses of chromosome arms 1p, 6q, 9p, 10q, 14q and 18q." (PMID 28193203, 2017). "Besides second NF2 copy inactivation, we found low somatic burden in both tumors and high level of genomic instability in the atypical meningioma." (PMID 28193203, 2017). "It is possible that the 25% of meningiomas with chromosome 22 loss that do not exhibit NF2 mutations nevertheless contain cryptic NF2-inactivating events." (PMID 28713588, 2017). "Not surprisingly, when we combined the benign and atypical samples together and simply compared non-NF2 mutants to NF2 mutant meningiomas (among which percentage of atypical tumours is much higher), we obtained a similar result, with NF2 mutants being genomically more unstable." (PMID 28195122, 2017). "The definite list of gene alterations in meningiomas with unaffected NF2 gene remains unknown and is under intensive investigations." (PMID 27429002, 2016). "Surprisingly, radiation-induced meningiomas rarely display NF2 alterations, both allelic losses and mutations in comparison to sporadic cases which may indicate that NF2 plays a less important role in the pathogenesis of radiation-induced meningiomas." (PMID 27429002, 2016). "Lastly, ~5.5% of benign meningiomas, or more than 10% of meningiomas without NF2 alteration, express mutations in SMO." (PMID 27458586, 2016). "So far, a range of NF2 mutations have been reported in meningiomas most of which consist of small insertions, deletions, or nonsense mutations affecting the splicing sites." (PMID 25965831, 2015). "We found a correlation of PDGFR-B expression and NF2 inactivation in a cohort of human meningiomas, and we showed that, in mice, Nf2 loss and PDGF over-expression in arachnoid cells induced meningioma malignant transformation, with 40% of Grade II meningiomas." (PMID 26418719, 2015). "In contrast, rapamycin treatment was not as effective as AZD2014 at suppressing NF2-deficient meningioma cell proliferation." (PMID 26219339, 2015). "We have demonstrated that Nf2 loss in arachnoid cells is sufficient to initiate meningioma development in mice, and identified a PGDS(Prostaglandin D2 synthase)-positive arachnoid cell as the cell of origin of meningioma." (PMID 26418719, 2015). "However, the exact importance of PDGF-B / PDGFR-B signaling in meningiomas remains elusive, especially in relation with NF2 inactivation." (PMID 26418719, 2015). "Neurofibromatosis 2 (NF2) is characterized by multiple nervous system tumors, including bilateral vestibular schwannomas, intracranial meningiomas, and spinal tumors such as schwannomas, meningiomas and ependymomas." (PMID 26219339, 2015). "Sporadic schwannomas, meningiomas, and ependymomas fund in patients who do not suffer from constitutional neurofibromatosis 2 have somatic NF2 mutations at rates of 42%, 27%, and 4%, respectively." (PMID 24393766, 2014).